C1orf122 (chromosome 1 open reading frame 122)
Synonyms: FLJ45459; ALAESM
Tractability: No criterion of Open Targets' tractability assessment is met for any kind of drug.
Gene: Protein-coding gene on chromosome 1 (37,806,979 to 37,809,454, forward strand). Ensembl gene ENSG00000197982.
Genetic constraint (gnomAD): Loss-of-function variants: 12 observed, 8.41 expected, observed/expected ratio (o/e) 1.43, 90% interval 0.89 to 1.91. That is too few expected variants to judge how well the gene tolerates losing a copy. Missense variants: 144 observed, 120.76 expected, observed/expected ratio (o/e) 1.19, 90% interval 1.04 to 1.37. Synonymous variants: 57 observed, 44.19 expected, observed/expected ratio (o/e) 1.29, 90% interval 1.04 to 1.61.
Homologues: Orthologues: macaque C1H1orf122 (97% identical), pig C1orf122 (97% identical), rabbit C1orf122 (97% identical), dog C1orf122 (95% identical), guinea pig C1orf122 (85% identical), mouse 1110065P20Rik (84% identical).
Diseases named in the same sentence as C1orf122 in open-access papers:
C1orf122 is named in the same sentence as 6 diseases in open-access papers, as found by Europe PMC text mining. Sharing a sentence is not in itself a finding about the gene and the disease. The quoted sentences say what the papers report.
breast carcinoma (1 paper, 2026). "Although an analysis of The Cancer Genome Atlas (TCGA) database revealed that C1orf122 is abnormally overexpressed in various cancer types, especially in HCC, non-small cell lung cancer, breast cancer, and other tumors, the specific biological function and mechanism of C1orf122 is not fully known." (PMID 41141389, 2026).
hepatocellular carcinoma (1 paper, 2026). A malignant tumor that arises from hepatocytes. "Although Chromosome 1 open reading frame 122 (C1orf122) is known to be a protein-coding gene, its biological functions and mechanisms in hepatocellular carcinoma (HCC) remain unknown." (PMID 41141389, 2026).
cancer (1 paper, 2026). A tumor composed of atypical neoplastic, often pleomorphic cells that invade other tissues. "A pan-cancer analysis was performed using the TCGA database to determine the differential expression of C1orf122 in HCC tissues and normal tissues." (PMID 41141389, 2026).
tumor (1 paper, 2026). "Overall, compared to normal tissues and cells, the HCC tumor cells and tissues exhibited a significantly higher C1orf122 expression, suggesting that C1orf122 contributed to the development of HCC and may predict the prognosis of HCC patients." (PMID 41141389, 2026). "Specifically, we performed WB analysis on seven of these tissue pairings and found that C1orf122 protein levels were significantly higher in tumor tissues than in adjacent non-tumor tissues." (PMID 41141389, 2026).
C1orf122 also shares sentences with these, for which no sentence is quoted: meningioma (1 paper); non-small cell lung carcinoma (1).